RIPOR1 (RHO family interacting cell polarization regulator 1)
Description:
Downstream effector protein for Rho-type small GTPases that plays a role in cell polarity and directional migration. Acts as an adapter protein, linking active Rho proteins to STK24 and STK26 kinases, and hence positively regulates Golgi reorientation in polarized cell migration upon Rho activation. Involved in the subcellular relocation of STK26 from the Golgi to cytoplasm punctae in a Rho- and PDCD10-dependent manner upon serum stimulation.
Synonyms: FAM65A; FLJ13725
Tractability: PROTAC: ubiquitination databases record sites on it.
Gene: Protein-coding gene on chromosome 16 (67,518,418 to 67,546,788, forward strand). Ensembl gene ENSG00000039523.
Subcellular location: Cytoplasm; Golgi apparatus
Subcellular location (Human Protein Atlas): Golgi apparatus; Cytosol
Gene Ontology:
Molecular function: 14-3-3 protein binding; protein binding
Biological process: cellular response to starvation; establishment of Golgi localization; positive regulation of cell migration; positive regulation of intracellular protein transport; protein localization to Golgi apparatus; response to wounding; Rho protein signal transduction
Cellular component: cytoplasm; cytosol; extracellular exosome; Golgi apparatus; membrane; vesicle membrane
Genetic constraint (gnomAD): Loss-of-function variants: 58 observed, 118.43 expected, observed/expected ratio (o/e) 0.49, 90% interval 0.4 to 0.61. The upper end of that interval is the gene's LOEUF score, 0.61, which puts it in group 2 of 6, group 1 being the genes least tolerant of losing a copy. Missense variants: 1,372 observed, 1,622.6 expected, observed/expected ratio (o/e) 0.85, 90% interval 0.81 to 0.88. Synonymous variants: 605 observed, 669 expected, observed/expected ratio (o/e) 0.9, 90% interval 0.85 to 0.97.
Homologues: Orthologues: chimpanzee RIPOR1 (99% identical), macaque RIPOR1 (95% identical), dog RIPOR1 (84% identical), pig RIPOR1 (82% identical), guinea pig RIPOR1 (81% identical), mouse Ripor1 (81% identical), rat Ripor1 (78% identical), rabbit RIPOR1 (73% identical), tropical clawed frog ripor1 (47% identical), zebrafish ripor1 (47% identical), Caenorhabditis elegans Y37A1A.4 (15% identical). Paralogues in human: RIPOR2 (31% identical), RIPOR3 (27% identical).
Diseases named in the same sentence as RIPOR1 in open-access papers:
RIPOR1 is named in the same sentence as 29 diseases in open-access papers, as found by Europe PMC text mining. Sharing a sentence is not in itself a finding about the gene and the disease. The quoted sentences say what the papers report.
cancer (2 papers, 2021 to 2022). A tumor composed of atypical neoplastic, often pleomorphic cells that invade other tissues. "Family with sequence similarity 65 member A (FAM65A), also known as RIPOR1, is differentially expressed between human tumor and non-tumor tissues in kinds of cancers." (PMID 35201499, 2021).
tumor (2 papers, 2021 to 2022). "Given that RHOA is generally considered an oncogene 50, we hypothesize that RIPOR1 may act as an oncogene or tumor suppressor in a context-dependent manner, although further investigations are warranted in the future." (PMID 35002526, 2022).
RIPOR1 also shares sentences with these, for which no sentence is quoted: colorectal cancer (2 papers); breast carcinoma (1); breast invasive carcinoma (1); cerebral cavernous malformation (1); cervical squamous cell carcinoma (1); cholangiocarcinoma (1); colon adenocarcinoma (1); endocervical adenocarcinoma (1); esophageal cancer (1); Glioblastoma multiforme (1); head and neck squamous cell carcinoma (1); hepatocellular carcinoma (1); immune disease (1); kidney cancer (1); lung adenocarcinoma (1); lung carcinoma (1); lung squamous cell carcinoma (1); neurodevelopmental disorder (1); ovarian carcinoma (1); pancreatic adenocarcinoma (1); paraganglioma (1); pheochromocytoma (1); prostate adenocarcinoma (1); skin cutaneous melanoma (1); stomach adenocarcinoma (1); tooth agenesis (1); uterine corpus endometrial carcinoma (1).